CD4 (CD4 molecule)
Diseases named in the same sentence as CD4 in open-access papers (continued):
Sharing a sentence is not in itself a finding about the gene and the disease.
respiratory infections (continued). "Murine models of respiratory infection with several viruses have been provided useful information about acute and chronic virus respiratory infection, humoral and cellular immune responses, CD4 and CD8 T cell biology, and innate immune responses." (PMID 17326843, 2007). "Additionally, three patients received antibiotic prophylaxis, two due to recurrent respiratory infections (one of whom was also receiving IgRT) and due to a reduced absolute count of CD4+ T cells and naïve CD4+ T cells, for which trimethoprim-sulfamethoxazole was administered." (PMID 40692796, 2025). "Towards the end of the first week of EHV-1 infection, T cells are attracted to the nasal cavity, intranasal T-cell numbers increase rapidly, and CD4+ and CD8+ T-cell proportions stay elevated even after the respiratory infection has cleared by two weeks pi." (PMID 39459849, 2024). "Rebultan (1995) reported that M. charantia significantly increased and normalized CD4 count and CD4/CD8 ratio in HIV-infected persons while reducing recurrent respiratory infections." (PMID 36678143, 2023). "During primary respiratory infection, naïve B cells, primed by either free antigen or antigen delivered by subcapsular sinus (SCS) macrophages, interact with cognate CD4+ T cells at the T-B border within the MLN." (PMID 34603321, 2021). "Depletion of both CD4+ and CD8+ T-cells in the lungs prior to respiratory infection was confirmed via flow cytometry." (PMID 28604843, 2017). "Prophylactic trimethoprim- sulfamethoxazole (TMP-SMX) 160/800 mg three times a week was initiated in patients with recurrent respiratory infections, independent of CD4+ counts." (PMID 40703516, 2025). "The administration of BT to older adults with a history of recurrent respiratory infections resulted in an expansion of naïve CD4 + T cells, recent thymic emigrants and stem cell-like memory CD8 + T lymphocytes, whereas the proportions of CD4 + and CD8 + T cells expressing PD1 were decreased." (PMID 37291596, 2023). "In addition, studies in animal models have also shown that adoptive therapy with CD4+ and/or CD8+ T cells can efficiently control respiratory infections including SARS-CoV-1, MERS, and influenza viruses." (PMID 36817441, 2023). "In a recent research, conducted in elderly subjects with a history of recurrent respiratory infections and no other chronic diseases, our group showed the ability of BT to significantly increase CD4+ naive T cells." (PMID 35155258, 2022). "The decreased IFN-γ response observed in mPGES-1-/- mice is likely due to a decrease in IFN-γ production by CD4+ and CD8+ T cells, as these cell types are the major producers of IFN-γ during MAV-1 respiratory infection (Mary McCarthy and Jason Weinberg, unpublished data)." (PMID 24147040, 2013). "Both CD4+ and CD8+ T-cells contribute to the clearance of Chlamydia in adult respiratory infection." (PMID 22724018, 2012). "However, the data accumulated thus far have sometimes been contradictory and, in any case, have not yet analyzed the priming events or APC that poise CD4 T cells elicited by respiratory infection to leave the dLN and migrate to the lung." (PMID 29681900, 2018). "We then examined the requirement for CD4+ and CD8+ T-cells in optimal host defense against respiratory infection with K. pneumoniae, as T-cells are not primarily thought to play a role in host defense against bacterial pathogens." (PMID 28604843, 2017).
Alzheimer disease (49 papers, 2007 to 2026). A progressive, neurodegenerative disease characterized by loss of function and death of nerve cells in several areas of the brain leading to loss of cognitive function such as memory and language. "In certain rat and APP transgenic mouse models of Alzheimer’s disease, for example, specific effector CD4+ T cells secreting IFN-γ, IL-17 or IL-22 were linked to increased neuroinflammation and exacerbation of disease progression." (PMID 26558367, 2015). "Alzheimer’s disease has previously been associated with shifts in non CMV-specific CD4 as well as CD8 T-cell subsets." (PMID 24155977, 2013). "A total of 17 immune cell characteristics were identified as potential mediators for 13 gut microbiota influencing Alzheimer’s disease, with Effector Memory CD4+ T-cell Absolute Count accounted for 8.99% of the causal relationship between genus Oscillibacter and Alzheimer’s disease." (PMID 39170894, 2024). "The same differences in innate immune response (except for monocyte subsets), lymphocytes and CD4+HLADR+ Tc were observed between patients with Alzheimer’s disease and ALE." (PMID 40303600, 2025). "In the 5XFAD Alzheimer’s disease mouse model, CD4+ T cells can induce expansion of an MHCII+ subset of microglia associated with increased amyloid beta uptake and enhanced effector CD4+ Th1 cell function." (PMID 41409145, 2025). "For example, GWAS SNPs associated with “Alzheimer’s disease and Lewy body co-pathology” are enriched in CD8 naive T cells and CD4 memory T cells meSNPs that colocalize with the GWAS SNPs." (PMID 37425926, 2025). "A study has pointed out that in Alzheimer’s disease (AD), there is extensive inferred communication between CD4+ T cells and CD8+ T cells." (PMID 39440247, 2024). "In patients with Alzheimer’s disease, a significant increase in CD4+ T lymphocytes has been observed, indicating an alteration in the post-thymic maturation of antigen-specific lymphocytes." (PMID 37801482, 2023). "A recent study reported AGAP3 in Alzheimer’s disease correlates with resting and naive CD4 cells, NK cells, CD cells, etc.." (PMID 37113989, 2023). "xCell analysis showed that most lymphocyte scores decreased in Alzheimer’s disease, including CD4+ Tc, CD4+ Te, Th1, natural killer (NK), natural killer T (NKT), pro-B cells, eosinophils, and regulatory T cells, except for Th2 cells." (PMID 36249779, 2022). "Ch25h has also been proposed as a susceptibility gene for Alzheimer’s disease and its deletion can significantly attenuate EAE disease course by limiting trafficking of pathogenic CD4+ T lymphocytes to the central nervous system." (PMID 27355629, 2016). "Studies have shown that patients with Alzheimer’s disease (AD) have elevated levels of CD4+/CD8+ T cells in peripheral blood, which is related to the permeability of the blood-brain barrier, which increases as the disease progresses, promoting the infiltration of T cells into the brain tissue." (PMID 37063844, 2023). "Alzheimer’s disease samples exhibited higher proportions of naive CD4 T cells, resting memory CD4 T cells, resting NK cells, monocytes, neutrophils and macrophages M2, whereas ND samples had higher levels of plasma cells, CD8+ T cells, follicular helper T cells, activated NK cells, and eosinophils." (PMID 37799623, 2023). "In addition to identifying novel individual genes, proceeding from our integrated Alzheimer’s disease mechanism network, we propose three disease initiating routes via extra-cellular ligands like CD4, DCN and IL8." (PMID 26784894, 2016). "Similarly, in Alzheimer’s disease, CD4+ T cells pass through the BBB into the brain." (PMID 39630234, 2025). "Indeed, the CD4+CD28null T-cell population can be elevated in age-related disease contexts such as those produced by cardiovascular disease, autoimmune disorders such as rheumatoid arthritis and multiple sclerosis, as well as in Alzheimer’s disease (AD)." (PMID 38963798, 2024).
Alzheimer disease (continued). "Regarding adaptive immunity, we found lower percentages of lymphocytes and Tc while CD4+CD8+ Tc and activated Tc were increased in Alzheimer’s disease compared with SD controls." (PMID 40303600, 2025). "An increase in CD4+ T cells and decrease in CD8+ T cells have been observed in patients with Alzheimer’s disease." (PMID 36118695, 2022). "mAbs (anti‐CD4 and anti‐CD40L) enable long‐term (>6 months) survival of hNSCs grafted into brains of laboratory mice and a mouse model of Alzheimer's disease." (PMID 36101963, 2022). "In this work, we report a low-grade infiltration of T cells (CD3+, CD4+ and CD8+) in the WM of aged individuals that is also observed at similar levels in patients with neurodegenerative disorders (Alzheimer ́s disease)." (PMID 33049712, 2020). "Microvesicles in the CSF of 15 patients with Alzheimer’s disease and 15 controls were analyzed by flow cytometry regarding the levels of CD3, CD4, CD45, CD64, BACE1, Aβ, APP and tau." (PMID 31068645, 2019). "According to this, blocking of IL-17A in a wild-type mouse model of lung Ad resulted in a decreased number of Foxp3+ Tregs and an increase of IFN-γ and TNF-α producing CD4+ T cells leading to a significant reduction of tumor growth." (PMID 22855687, 2012). "We focused on a subset of CD4‐derived double‐negative T (DNT) cells called TCRαβ+NK1.1−CD4−CD8− for treating Alzheimer's disease, and we found their injection can improve cognition of the 5×FAD mouse model." (PMID 39844773, 2025). "For example, icariin exerts neuroprotective effects via modulating the CD4+ T lymphocyte-related immunoinflammatory responses in APP/PS1 mice and may be a promising drug against Alzheimer’s disease progression." (PMID 33714945, 2021). "The effect of Alzheimer’s disease (AD) medications on CD4+ T cells homing has not been thoroughly investigated." (PMID 32948022, 2020). "Whether the observed negative correlation between MUC1 and activated CD4 T cells in Alzheimer’s disease patients is valid, warrants further investigation." (PMID 38711596, 2024). "Besides finding the microRNAs that could regulate the critical nodes such as APP, BACE1, CD4, DCN, IL8 and PSEN1, we searched to uncover additional regulatory mechanisms of Alzheimer’s disease genes." (PMID 26784894, 2016). "CSF CD4+HLADR+ and CSF/PB CD8+HLADR+ were the most relevant parameters when comparing antibody-negative ALE and Alzheimer’s disease, CSF CD4+HLADR+, PB iMono, CSF CD4+/CD8+ ratio when comparing antibody-negative ALE and FTD." (PMID 40303600, 2025).
measles (49 papers, 2007 to 2025). A highly contagious viral infection caused by the measles virus. "Being born after 1983 is strongly associated with seronegativity against measles (p = 0.00) and a nadir CD4 cell count below 200/mm3 is independently associated with rubella seronegativity (p = 0.013)." (PMID 30362663, 2018). "High dose measles vaccinations in Africa during the 1990s were found to be associated with higher mortality in infants, due to infectious diseases, a reduced CD4/CD8 ratio, and mitogeninduced lymphocyte proliferation." (PMID 21191455, 2010). "For example, the use of a trivalent live-attenuated vaccine against measles, mumps, and rubella is contraindicated in PWH with a CD4 cell count <200 cell/mm3 for the high risk of developing the disease." (PMID 37243000, 2023). "In all of 17 seronegative, naïve individuals, bone marrow did host SARS-CoV-2 cross-reactive memory CD4+ T cells, at absolute numbers of 106 to more than 107, numbers about the same as those of measles-, rubella-, or mumps-specific memory CD4+ T cells." (PMID 36268016, 2022). "Both, CD8+ and CD4+ T cells, which play significant roles during the rash phase of measles, express estrogen receptors (ERa and ERb) and are estrogen sensitive." (PMID 35410143, 2022). "In chronic measles and distemper, often this multicentric repopulation is accompanied by CD4- and CD8-dominated inflammatory responses in the CNS." (PMID 30936878, 2019). "Among 18.7% measles, 23.5% mumps, 35% rubella and 7.1% varicella IgG seronegative patients CD4 cell count was less than 200/mm3." (PMID 30362663, 2018). "We performed Next Generation Sequencing (mRNA-Seq) of intracellular miRNAs in measles virus-stimulated B and CD4+ T cells from high and low antibody responders to measles vaccine." (PMID 29381765, 2018). "In peripheral blood mononuclear cells (PBMC) of prodromal measles patients, we detected MV-infected memory CD4+ and CD8+ T cells and naive and memory B cells at similar levels as those observed in NHPs." (PMID 30470742, 2018). "Analysis of the composition of T cell subsets before and after measles showed a decreased frequency of CD4+ naive T cells and increased frequencies of CD4+ Tcm and CD8+ Temro." (PMID 30470742, 2018). "It has been reported that CD4+ memory T cells specific for cytomegalovirus, tetanus toxoid, measles, mumps and rubella are enriched in the bone marrow." (PMID 29186194, 2017). "This contrasts with a study of circulating lymphocytes in children infected with measles, where the CD4+/CD8+ ratio was still decreased in infected subjects at up to 1 month following infection." (PMID 24559207, 2014). "In vitro responses to measles are dominated by CD4+ T cells that, depending on antigen dose, primarily produce a Th1-like pattern of cytokine release." (PMID 23226275, 2012). "Children with CD4+ T-cell counts lower than 25% had significantly low levels of antibodies, particularly to the live attenuated measles vaccine." (PMID 18060056, 2007). "Furthermore, we investigated how the control of acute viremia relates to the skin rash observed during measles infection because the measles skin rash is indicative of CD4+ and CD8+ T-cell responses against measles." (PMID 34007460, 2021). "It was previously shown that N321–350 evokes CD4+ responses in measles convalescent-phase donors." (PMID 32636246, 2020). "One might therefore predict that this would impact cellular responses to vaccination, although this has not been investigated except for the one study showing an early decline in measles-specific CD4 T cell IFN-γ responses in HCMV infected infants." (PMID 32582177, 2020). "We have since repeated this finding of a significant negative correlation between baseline Tregs and MV antibodies using a different Treg definition (CD4+CD25hiFOXP3+) and different time point (2 weeks post-measles vaccination) in a separate prospective cohort (in preparation)." (PMID 28855899, 2017).
measles (continued). "The long distances between some health centers and the national level - in addition to difficult driving conditions in some areas - contributes to a situation where specimens arrive at the NRL in inadequate condition (for example, hemolyzed samples for CD4 and measles IgM testing)." (PMID 21702948, 2011). "Together with the plethora of data reporting the SARS-CoV-2-reactive, circulating memory CD4+ T cells, the present data demonstrate that there is also a preexisting potent population of bone marrow-resident memory CD4+ t cells, comparable to those reactive to measles, mumps, or rubella." (PMID 36268016, 2022). "The intraepithelial reaction may involve either CD8 or CD4 T-cytotoxic cells and is analogous to a viral exanthema of the skin, such as measles and smallpox, which occur when the immune response against these infections is activated and the infected cells are attacked by T-cytotoxic cells." (PMID 30641955, 2019). "In approximately half the children in this study, the percentage of CD4-positive T cells decreased to <30% of the total number of lymphocytes at PICU admission, which suggests that measles-associated immune suppression may have resulted in increased susceptibility to AdV7 infection." (PMID 26926035, 2016). "Similarly, this mechanism could also explain reductions in HIV-1 loads during acute measles: MV infection of memory CD4+ T-lymphocytes could result in depletion of HIV-1-infected cells." (PMID 22952446, 2012). "It is likely that an increased number of CD4+ T cells following highly active antiretroviral therapy (HAART) may lead to a new generation of measles-specific memory B cells through repeated antigenic exposure in countries with high measles prevalence." (PMID 21347342, 2011). "It would be interesting to look at the CD4/CD8 T-cell profile in skin at the application site of HD-MAP vaccinations containing live-attenuated virus vaccines, for example, measles, mumps, rubella, that can replicate in the host cells." (PMID 34329337, 2021). "For all children, blood samples were taken to measure anti-measles IgG by EIA and CD4 count by flow cytometry." (PMID 30567502, 2018). "PLWH with CD4 percentages ≥15% and a CD4 count ≥ 200 cells/mm3 for at least 6 months and lacking evidence of immunity to measles, mumps, or rubella are advised to undergo a two-dose series with a minimum interval of 4 weeks." (PMID 40872885, 2025). "EFNB2 is a receptor for Hendra and Nipah virus, CD4 for human immunodeficiency virus, CXADR is the coxsackievirus and adenovirus receptor, and BSG has been shown to be involved in infection of measles and human cytomegalovirus." (PMID 38140653, 2023). "BHIVA guidelines recommend that HIV‐positive adults be screened for measles IgG regardless of a history of childhood vaccination and that measles seronegative patients with CD4 cell counts >200 are vaccinated with MMR." (PMID 30362663, 2018). "Secondly, children without evidence of severe immunosuppression i.e. their CD4 count is more than 15%, should be vaccinated against measles." (PMID 30567502, 2018). "We first assessed miRNA expression in purified MV-stimulated B and CD4+ T cells irrespective of immune response status to measles vaccination (i.e., overall analysis in all samples to assess the effect of viral stimulation)." (PMID 29381765, 2018). "We found lower CD4 and CD8 cell counts in AME patients compared to measles control patients, which could reflect the preferential induction of Th2 cytokines and blockade of T cell proliferation described elsewhere." (PMID 23967232, 2013). "Moreover, antibody concentration after a single dose of the measles vaccine was substantially lower than expected, particularly low in HIV-infected children with low CD4+ T cell counts." (PMID 18060056, 2007).
measles (continued). "However, MeV-induced innate responses likely influence the adaptive responses to infection that lead to virus clearance and protective immunity as IL-18 and IL-1β influence the CD4 and CD8 T cell differentiation phenotypes that characterize recovery from measles." (PMID 36851476, 2023). "Although the authors did not test the in vivo depletion of CD4-positive cells, they hypothesized that the CD4-positive T cell-mediated immune response specific for measles gene products was sufficient to control measles virus infection." (PMID 33534867, 2021). "However, CD4 count was lower among children with negative serostatus to measles (23% versus 32%, p < 0.001)." (PMID 30567502, 2018). "In a study of measles vaccine in Gambian infants, 1 week after vaccination infant CD8 T-cell responses did not vary with CMV infection acquired congenitally or postnatally, but CD4 T-cell IFN-γ responses were lower in CMV-infected infants than in infants without CMV infection." (PMID 29552009, 2018). "The inverse correlation between the circulating CD4+FOXP3+CD127− Tregs post-DTP vaccination and the postvaccination IFN-γ:IL-10 ratio in TT and measles peptide cultures, but not PPD or αCD3/αCD28, may support a vaccine-specific immunoregulatory role." (PMID 28855899, 2017).